ENSG00000281613 (novel ret finger protein-like 4B)
Gene: Protein-coding gene on chromosome 6 (112,236,806 to 112,350,094, forward strand). Ensembl gene ENSG00000281613.
Genetic constraint (gnomAD): Loss-of-function variants: 0 observed, 0.0826 expected, observed/expected ratio (o/e) 0, 90% interval 0 to 1.89. That is too few expected variants to judge how well the gene tolerates losing a copy. Missense variants: 163 observed, 169.11 expected, observed/expected ratio (o/e) 0.96, 90% interval 0.85 to 1.1. Synonymous variants: 61 observed, 65.42 expected, observed/expected ratio (o/e) 0.93, 90% interval 0.76 to 1.15.